DNAJB8 (DnaJ heat shock protein family (Hsp40) member B8)
Description:
Efficient suppressor of aggregation and toxicity of disease-associated polyglutamine proteins.
Synonyms: MGC33884; CT156; DJ6
Tractability: No criterion of Open Targets' tractability assessment is met for any kind of drug.
Gene: Protein-coding gene on chromosome 3 (128,462,437 to 128,466,968, reverse strand). Ensembl gene ENSG00000179407.
Gene Ontology:
Molecular function: protein folding chaperone; protein-folding chaperone binding; Hsp70 protein binding
Biological process: negative regulation of inclusion body assembly; protein folding
Cellular component: cytosol; nucleus; cytoplasm
Genetic constraint (gnomAD): Loss-of-function variants: 0 observed, 0.75 expected, observed/expected ratio (o/e) 0, 90% interval 0 to 1.79. That is too few expected variants to judge how well the gene tolerates losing a copy. Missense variants: 322 observed, 294.57 expected, observed/expected ratio (o/e) 1.09, 90% interval 1 to 1.2. Synonymous variants: 112 observed, 120.07 expected, observed/expected ratio (o/e) 0.93, 90% interval 0.8 to 1.09.
Homologues: Orthologues: chimpanzee DNAJB8 (99% identical), rabbit DNAJB8 (93% identical), pig DNAJB8 (90% identical), dog DNAJB8 (88% identical), rat Dnajb8 (85% identical), guinea pig DNAJB8 (83% identical), mouse Dnajb8 (82% identical), zebrafish dnajb6b (53% identical), zebrafish dnajb1a (34% identical), zebrafish dnajb1b (34% identical), Drosophila melanogaster CG5001 (32% identical), Drosophila melanogaster CG2887 (31% identical), and 7 more. Paralogues in human: DNAJB6 (64% identical), DNAJB2 (49% identical), DNAJB7 (47% identical), DNAJB4 (35% identical), DNAJB5 (34% identical), DNAJB11 (31% identical), DNAJB1 (31% identical), DNAJB14 (29% identical), DNAJB12 (29% identical), DNAJB13 (28% identical), DNAJB9 (26% identical).
Diseases named in the same sentence as DNAJB8 in open-access papers:
DNAJB8 is named in the same sentence as 11 diseases in open-access papers, as found by Europe PMC text mining. Sharing a sentence is not in itself a finding about the gene and the disease. The quoted sentences say what the papers report.
renal cell carcinoma (4 papers, 2016 to 2021). "In the same study, DnaJB8 knockout in renal cell carcinoma cells conferred them sensitivity to docetaxel, thus indicating a link between HSP40 and drug resistance intrinsic to CSCs." (PMID 32268506, 2020). "In a previous study, we showed by gene knockdown using siRNA and gene overexpression experiments that Dnaj (Hsp40) homolog, subfamily B, member 8 (DNAJB8), a role in the maintenance, of renal cell carcinoma CSCs/CICs." (PMID 26751205, 2016). "In a previous study, we found that DNAJB8 is expressed in CSCs/CICs derived from mouse and human renal cell carcinoma (RCC) line cells RenCa and ACHN, and we found by using siRNA technology that DNAJB8 has a role in the maintenance of RCC CSCs/CICs." (PMID 26751205, 2016). "We reported that DNAJB8 is expressed preferentially in CSCs/CICs derived from renal cell carcinoma (RCC) and colorectal cancer and that DNAJB8 has an important role in the maintenance of CSCs/CICs." (PMID 26751205, 2016). "In the present study, we established Dnajb8 knockout (KO) renal cell carcinoma (RCC) line cells (RenCa cells) and analyzed the cells to confirm the function of Dnajb8 in RCC CSCs/CICs." (PMID 26751205, 2016). "DNAJB8 is also identified as a factor that induces cancer stem-like properties, such as tumor-initiating ability and drug resistance in human CRC and renal cell carcinoma (RCC) cell lines." (PMID 34948322, 2021).
colon cancer (3 papers, 2022 to 2025). "Our results showed that the resistance of colon cancer cells to both 5-FU increased following DNAJB8 upregulation, which suggests that DNAJB8 may promote the multidrug resistance of COAD through MDR1." (PMID 35165262, 2022).
infertile (3 papers, 2020 to 2023). "Similar to DNAJB7, Dnajb8 is predominantly in haploid male germ cells but dispensable for spermatogenesis, although Dnajb8 transcripts are downregulated in the spermatozoa of infertile men compared to those of fertile men." (PMID 37004113, 2023). "Notably, Dnajb8 was downregulated in spermatozoa of infertile men by 12-fold compared to that of normospermic individuals." (PMID 33391882, 2020). "DNAJB8 is a heat shock binding protein that regulates the ATPase activity of HSP70, which is a crucial protein for male fertility and spermatogenesis, and it shows reduced RNA levels in infertile men." (PMID 33292187, 2020).
bone sarcoma (1 paper, 2020). A sarcoma that arises from the bone. "The T-cell-engaging bispecific antibody targeting DNAJB8, B10-(CD3xJB8), might hold promise for antibody-based therapy in patients with carcinoma and bone sarcoma." (PMID 32753678, 2020).
cervical cancer (1 paper, 2016). A primary or metastatic malignant neoplasm involving the cervix. "DNAJB8 localizes in the cytoplasm of HeLa cervical cancer cells; however, we observed that some of DNAJB8 can localize in the nucleus of HEK293 cells (data not shown)." (PMID 26751205, 2016).
kidney cancer (1 paper, 2020). Primary or metastatic malignant neoplasm involving the kidney. "Notably, an increase in the amounts of the SP cells and SOX2 expression was found in kidney cancer cells being subjected to heat stress; by means of DnaJB8 knockdown with siRNAs, it was shown that the observed effects were due to HSF1-induced DnaJB8 upregulation." (PMID 32268506, 2020).
cancer (14 papers, 2016 to 2024). A tumor composed of atypical neoplastic, often pleomorphic cells that invade other tissues. "Enhanced expression of DNAJB8 has also been observed in stem cells derived from cancer (CSCs) in patients diagnosed with renal cell carcinoma." (PMID 38339390, 2024). "DNAJB8 is well established as an effective immunotherapy target in cancer stem cells (CSCs) and cancer-initiating cells (CICs) due to its identified functions in the maintenance of CSCs and CICs of renal cell carcinoma." (PMID 36499297, 2022). "Recently, it has been reported that DNAJB8 is a testicular cancer antigen and a cancer stem-like cell antigen involved in renal cell carcinoma." (PMID 35165262, 2022). "It has been suggested that cellular stress activates HIF-1 to promote the expression of DNAJB8, which induces cancer stem cell-like cells." (PMID 34912211, 2021). "As CSC/CIC have been thought to be essential for tumor maintenance, recurrence, and distant metastasis, the engineering and administration of DnaJB8-specific cytotoxic T lymphocytes exhibited a significant anti-cancer activity in vivo." (PMID 31878360, 2019). "We thus performed gene knockout of Dnajb8 using the CRISPR/Cas9 system to address the function of Dnajb8 in cancer cells." (PMID 26751205, 2016). "For example, DNAJB8 was shown to be a novel target of cancer stem-like cell/ cancer-initiating cell (CSC/CIC)-targeting immunotherapy of colon cancer." (PMID 26993597, 2016). "Studies suggest that export of DnaJB11 enhances extracellular proteostasis, that intercellular movement of DnaJB1 or DnaJB6 enhances the proteostasis capacity in recipient cells, whereas the import of DnaJB8 increases resistance to chemotherapy in recipient cancer cells." (PMID 36581212, 2023). "Importantly, some DNAJB proteins, including DNAJB1/HDJ1, DNAJB4/HLJ1, DNAJB6/MRJ, DNAJB8, DNAJB9/MDG1/ERdj4, DNAJB11/ERdj3/HEDJ, and DNAJB12, are implicated in cancer progression." (PMID 34948322, 2021). "DNAJB8 is a cancer-testis antigen that is being investigated as another RCC antigen target, expressed in cancer stem-like cells and cancer initiating cells." (PMID 38539542, 2024). "DNAJ (HSP40) homolog subfamily DNAJB8 belongs to the HSP40 family, and its expression was detected in the development and metastasis of cancer." (PMID 38339390, 2024). "In this study, we developed a therapeutic single-chain variable-fragment (scFv) antibody that recognises the cancer stem-like cell/cancer-initiating cell (CSC/CIC) antigen, DNAJB8." (PMID 32753678, 2020). "DNAJB8 is a cancer stem-cell/cancer-initiating antigen and not expressed in normal organs, except for testis lacking HLA expression like cancer–testis antigen." (PMID 32753678, 2020). "Similarly, DnaJB8, which is HSP40 subfamily, is highly expressed in cancer stem-like cell/cancer-initiating cell (CSC/CIC) isolated from colorectal cancer compared with non-CSC/CIC." (PMID 31878360, 2019). "However, the mechanism by which DNAJB8 affects the maintenance of cancer stem cells has not been clarified." (PMID 26751205, 2016).
tumor (7 papers, 2016 to 2022). "As a new regulatory mechanism of DNAJB8 in tumor progression, the functional importance of maintaining CSCs and CICs has been highlighted to develop novel therapeutic strategies." (PMID 36499297, 2022). "The results indicate that Dnajb8 has a role in tumor initiation, side population ratio and sphere formation but it is dispensable for stress responses." (PMID 26751205, 2016). "Dnajb8 has a role in sphere formation, ratio of SP cells and tumor initiation; however, it is dispensable for stress responses." (PMID 26751205, 2016). "In that study, we observed that DNAJB8 knockdown suppressed tumor growth; however, tumor growth was also observed in mice injected with DNAJB8 knockdown ACHN human RCC cells." (PMID 26751205, 2016). "An in vivo single cell tumor initiation assay revealed that the numbers of CSCs/CICs were 3 in 4 wild-type RenCa cells and 1 in 4 Dnajb8 KO cells." (PMID 26751205, 2016). "Moreover, serum DNAJB8 levels decreased after tumor resection, indicating that serum DNAJB8 was mainly produced by COAD cells." (PMID 35165262, 2022). "Although DNAJB8 facilitates tumor development and progression, whether DNAJB8 is involved in tumor metastasis remains unclear." (PMID 36499297, 2022). "We could not conclude whether the tumor initiation observed in DNAJB8 knockdown cells were due to incomplete gene knockdown or whether DNAJB8 has a partial role in the tumor initiation." (PMID 26751205, 2016). "The incomplete inhibition of tumor initiation by syngeneic transplantation suggests that regulation of gene expression by DNAJB8 may not be as solid as that by stem cell-related transcription factors." (PMID 26751205, 2016). "In this study, DNAJB8 KO cells showed no DNAJB8 protein expression, and those cells showed reduced tumor initiation ability but could still initiate a tumor as revealed a single cell injection assay." (PMID 26751205, 2016).
neurodegenerative disease (1 paper, 2019). A disorder of the central nervous system characterized by gradual and progressive loss of neural tissue and neurologic function. "However, as DNAJB8 is almost exclusively expressed in the testis, it is unlikely to play a protective role against the development of neurodegenerative diseases." (PMID 31514384, 2019).
DNAJB8 also shares sentences with these, for which no sentence is quoted: colorectal cancer (1 paper); renal carcinoma (1).